LEP (leptin)
Diseases named in the same sentence as LEP in open-access papers (continued):
Sharing a sentence is not in itself a finding about the gene and the disease.
cancer (continued). "Nonetheless, adipose tissue plays a key role in physiological processes, a disturbed expression level of leptin was observed in the course of cancer." (PMID 32531934, 2020). "Leptin and its receptor are overexpressed in cancer tissues compared with healthy epithelium and benign lesions and were found to be associated with a higher incidence, increased progression, and poor prognosis of several human cancers." (PMID 32526957, 2020). "Other secreted-proteins, such as MPS-1, ICAM-1, and PLOD2, have also been validated as critical downstream effectors of leptin in cancers." (PMID 33371368, 2020). "Given the pro-inflammatory effect of leptin on T cells, leptin is being investigated for use in cancer treatment to enhance the tumor-fighting action of T cells." (PMID 33584724, 2020). "Although some studies report that serum leptin is lower in cancer patients in comparison to healthy individuals, few studies have investigated leptin in cancer cachectic conditions." (PMID 32660156, 2020). "Leptin gene expression is up-regulated by pro-inflammatory cytokines, such as TNFα and IL-1, which are also involved in the pathophysiology of cancer cachexia." (PMID 32660156, 2020). "In cancer, the installation of hypoxic conditions is a driver of leptin secretion through hypoxia-induced factor-1 (HIF-1) that activates the leptin gene promoter in adipocytes and fibroblasts." (PMID 32354024, 2020). "Leptin and adiponectin, the most important adipokines, have partially contradictory functions in cancer cell behavior." (PMID 32092997, 2020). "We and others have shown that leptin signaling impacts several pathways involved in cancer, and specifically in BC development." (PMID 32471192, 2020). "Leptin acts as an adipocytokine functions via the leptin receptor, which stimulates growth, migration, and invasion of cancer cells." (PMID 32596369, 2020). "Future research should focus on the conformational changes of intracellular signaling altered by elevated levels of leptin and their relationship with pathological mechanisms in cancer." (PMID 33334030, 2020). "Some of the metaboendocrine effects of CR—including improved insulin sensitivity, reduced leptin, and increased ghrelin—have been independently considered as approaches for intervention in cancer cachexia." (PMID 33224954, 2020). "The parallelism between leptin and Sam68 in their ability to promote cancer cells indicates that Sam68 is an intracellular mediator involved in leptin activity in cancer cells." (PMID 32033341, 2020). "Subsequently, the effect of adipocyte-derived leptin on miR-34a expression in cancer cells was evaluated." (PMID 33371368, 2020). "Leptin has pro-tumorigenic effects, such as increasing cancer cell proliferation, self-renewal, angiogenesis, and survival." (PMID 32326381, 2020). "The researchers went on to explain that LEPR overexpression has a fundamental role in breast carcinogenesis, since it enables cancer cells to internalize circulating leptin." (PMID 33213024, 2020). "Leptin is able to modulate the hallmarks of cancer development and progression, also through a functional interplay with other important molecular effectors, including estrogens, growth factors, and inflammatory cytokines." (PMID 32526957, 2020). "High serum levels of leptin, which are strongly correlated with adipose tissue mass, are recognized as a factor driving cancer development and progression, as leptin exhibits mitogenic, proinflammatory, anti-apoptotic, and proangiogenic properties." (PMID 32968152, 2020). "Leptin promotes tumor progression, by inducing signaling pathways that regulate cell migration and invasion and the maintenance of cancer stem cells and metastasis." (PMID 33334030, 2020). "Accordingly, miR-34a repression was critical for leptin/OBR-induced upregulation of PAI-1 in the adipocyte-cancer cell interaction." (PMID 33371368, 2020).
cancer (continued). "Intriguingly, adipose tissue-derived leptin has been positively associated with PI3K/Akt pathway activation and radio/chemotherapy resistance in cancer cells, further confirming the importance of BMAs in the bone marrow metastatic microenvironment." (PMID 32527062, 2020). "In later studies, this group identified that interactions between LPS-TLR4-NANOG and Leptin-Ob-R-STAT3 pathways are crucial to enhance TICs role in malignant tumor development and metastasis." (PMID 33316927, 2020). "Cancer cells trap the influence of leptin through overexpression of the leptin receptor (Ob-R) that is normally expressed predominantly in the hypothalamus and at lower levels in other parts of the body (e.g., breast epithelial cells and pancreas)." (PMID 32354024, 2020). "Although adipokine-mediated crosstalk, such as IL-6, leptin, resistin, and autotaxin, has been highlighted in adipocyte-cancer cell interactions, the detailed mechanisms are not fully defined." (PMID 33371368, 2020). "Leptin can affect also the adhesion of cancer cells to the extracellular matrix (ECM) and the proteolysis of ECM components, essential steps in tumour metastasis." (PMID 32033341, 2020). "A growing body of evidence has raised the important role of leptin, an adipokine mainly produced by adipocytes but also by epithelial tumor cells itself and by other stroma cells, as an active player involved in cancer development and progression." (PMID 32526957, 2020). "It is meaningful to compare the functional impact of the intrinsic PAI-1 and the leptin-induced PAI-1 for cancer cells." (PMID 33371368, 2020). "In in vitro models using several cancer cell lines, it was found that leptin promotes the expression of mesenchymal markers, a decrease in epithelial markers, and an increase in cell migration and invasion." (PMID 33334030, 2020). "In recent years, leptin has been found to promote cell migration and invasion, the maintenance of cancer stem cells, the inhibition of apoptosis, and the induction of EMT in cancer cells." (PMID 33334030, 2020). "Stimulatory effect of leptin on cell growth and proliferation was observed in normal and cancer cells of the prostate." (PMID 32455738, 2020). "Given the variable roles and observations, the precise role of leptin in cancer remains to be resolved through additional clinical and experimental research." (PMID 33050319, 2020). "Increased cytokine interleukin-6 and leptin lead to elevated CYP1B1 activity, which possibly causes cancer." (PMID 32626511, 2020). "In this study, we screened for secreted proteins in the co-cultured cancer cells and confirmed leptin as a positive regulator of PAI-1." (PMID 33371368, 2020). "It is possible that in advanced stages of cancer strong oncogenes takes over the processes and the LEP system is overwhelmed at least in some cases." (PMID 31592340, 2019). "These include hormones and other messages important in cancer regulation, including leptin, ghrelin, glucose, dietary amino acids, and changes in extracellular pH and CO2 concentrations." (PMID 31773065, 2019). "Leptin can be considered not only as a new biomarker for cancer diagnosis but also as a therapeutic target for personalized treatment regimens." (PMID 30803210, 2019). "In triple-negative breast cancer, leptin-dependent mechanisms, which lead to cancer, mediated by the upregulation of stem cell (CSC)- and EMT-related gene expression, induces estrogen receptor-α (ER-α) expression via JAK-STAT pathway." (PMID 31141984, 2019). "In this regard, several pro-inflammatory cytokines have been shown to contribute to anorexia in cancer, per se, but also enhancing the availability of neuropeptides acting at the central nervous system level such as melanocortin, neuropeptide Y, or leptin." (PMID 30833900, 2019). "Among the adipokines produced by ASCs, leptin and interleukin-8 (IL-8), have been shown to mediate cancer proliferation, migration and invasion." (PMID 31817072, 2019).
cancer (continued). "Leptin signaling enhances tumor formation, proliferation and invasion by activation of cancer stem cell signaling pathways." (PMID 31380268, 2019). "The study of isolated cancer stem cells revealed that their proliferation was stimulated in the presence of anticancer therapies (tamoxifen, fulvestrant, doxorubicine) and leptin." (PMID 31756890, 2019). "Seven of these biomarkers (TNFα, sFasL, SCF, VEGF, leptin, prolactin, OPN) were also significantly elevated in the cancer-associated cluster compared to the high diversity/inflammation cluster (P ranging from 0.02 to <0.0001)." (PMID 31089160, 2019). "Leptin indirectly affects prostate cancer cell growth via promoting bone resorption, and increased expression of IL-1β drives cancer cell colonization of BMA in breast cancer." (PMID 31334678, 2019). "We had previously shown the role of leptin in interfering with anti-cancer treatments, and herein we wanted to see if leptin had any activity on cancer stem cells (CSCs)." (PMID 31756890, 2019). "Nevertheless, some authors reported that in advanced cancers LEP expression diminishes, suggesting silencing of LEP expression in an advanced stage, which indicates the anti-tumorigenic role of the LEP." (PMID 31592340, 2019). "The presence of only high level of circulating LEP cannot be sufficient to produce excessive growth promotion leading to cancer; it must need the receptor." (PMID 31592340, 2019). "Accumulating evidence has suggested that leptin (LEP) is very important for the development of cancer." (PMID 30697798, 2019). "More recently, leptin has been proposed to promote cancer stem cells (CSC) enrichment and epithelial-to-mesenchymal transition (EMT) phenotype by upregulating the expression of multiple CSC/EMT–related genes." (PMID 31380268, 2019). "It has been shown that leptin and resistin stimulate the Akt signaling in cancer cells, and hyperactivated Akt pathway was associated with increased protein levels of FASN and Cav-1." (PMID 29568521, 2018). "Consistently, chronic treatment with leptin induces an increase in the population of cancer stem cells in the MDA-MB-231 cultured model." (PMID 30404206, 2018). "Previous studies have shown that leptin enhances mammosphere forming ability of MCF-7 cells, and thus, suggested leptin helps in augmenting the cancer stem cell (CSCs)/tumor initiating cells (TICs) properties in less aggressive BC cells." (PMID 29370782, 2018). "MAPK signaling was activated to enhance AP-1 binding to VEGF-A promoter for transactivation by leptin-leptin receptor axis in cancer cells." (PMID 29682217, 2018). "Increasing evidence demonstrates that the JAK/STAT3, PI3K/AKT and MEK/ERK pathways are frequently activated by adipokines, such as IL-6 and leptin and that these pathways are often altered in several types of cancer." (PMID 30563531, 2018). "In this review, we focus on the pathological function of leptin-leptin receptor in cancer, and further illustrate the clinical significance based on the correlation with cancer patient outcomes." (PMID 29682217, 2018). "Emerging evidences has indicated leptin's function in promoting several processes which are relevant to cancer progression including cell proliferation, metastasis, angiogenesis and drug resistance." (PMID 29682217, 2018). "According to the previous findings in publications and in silico analysis from the clinical cancer databases, the expressions of leptin and leptin receptor are found in many types of cancer." (PMID 29682217, 2018). "Low levels of adiponectin and high levels of leptin are seen in obesity and/or DM2, and this profile is associated with increased cancer risk." (PMID 29361779, 2018). "Leptin had been pointed out to regulate cell proliferation particularly in various type of cancer cells." (PMID 29682217, 2018). "Our results, together with those of previous studies, support the contention that the effects of adiponectin on cancer cells are opposite to those of leptin." (PMID 29603059, 2018).
cancer (continued). "It is well documented that leptin, an adipocyte-secreted hormone, has opposite effects on the proliferation of cancer cells." (PMID 29603059, 2018). "In the same way, another study documented increased cancer cell migration/invasion through leptin-mediated activation of RhoA/ROCK, PI3/AKT and JAK/STAT3 pathways." (PMID 30510663, 2018). "The effects of leptin-Notch/RBP-Jk signaling on cancer cell proliferation, apoptosis, and drug resistance require more investigation." (PMID 30004402, 2018). "It is known that leptin and Notch signaling mediate the activation of cancer stem cells that can affect drug resistance." (PMID 30004402, 2018). "Anti-apoptotic and mitogenic effects of leptin have been demonstrated on different cancer cell lines." (PMID 30154386, 2018). "Leptin has shown significant stimulatory effects on growth and metabolism in cancer cell lines, for instance MCF-7 breast cancer cells, in which it induced increased expression of PGC1α and MFN2, mitobiogenesis and respiration." (PMID 29361779, 2018). "The studies have reported that adinopectin (Adipoq), leptin (Lep), ghrelin (Ghr), and insulin-like growth factor (Igf1) hormones have an important role in the cancer development and immunity." (PMID 29511668, 2018). "In this sense, in MCF7 cells, leptin also confers resistance to tamoxifen, an anti-estrogen treatment commonly used in cancer patients." (PMID 30404206, 2018). "It is thought that cancer progression, continued inflammation, and catabolic processes lead to decrease of serum leptin concentration." (PMID 30510663, 2018). "We relatively display leptin and leptin receptor expression levels in pan-cancer panel based on the transcriptome analysis via dataset The Cancer Genome Atlas (TCGA), and show the clinical association of the axis in predicting cancer prognosis." (PMID 29682217, 2018). "IL-6 and leptin were identified as important factors involved in cancer progression in a study examining the over-production of inflammatory cytokines due to chronic low-grade inflammation." (PMID 30563531, 2018). "Secreted leptin sustains short autocrine-paracrine loops and targets cancer epithelial cells to enhance their growth, motility and invasive behaviors." (PMID 29370782, 2018). "We also found leptin to increase the stemness of both cancer cell lines, as indicated by aldefluor activity, CD44/CD24 expression, and mammosphere formation." (PMID 28542577, 2017). "Leptin plays an important role in diet control; however, it has a stimulatory potential on cancer cell proliferation." (PMID 28750624, 2017). "Recent studies have demonstrated that this hormone stimulates growth, migration, invasion and angiogenesis in tumour cell models, suggesting that leptin is capable of promoting an aggressive cancer phenotype." (PMID 28861689, 2017). "As one of explanations for the fact that leptin-LepRb expression group had poor survival, researchers suggested that leptin-LepRb counteracted apoptosis in cancer cells." (PMID 28316984, 2017). "In the present study, we found that the AMPK/FoxO3A axis is involved in leptin-induced autophagy activation and contributes to the growth of cancer cells." (PMID 29312618, 2017). "Previously, our study group also showed a decrease in leptin plasma level and mRNA content in the subcutaneous white adipose tissue of cancer cachetic patients." (PMID 28830524, 2017). "In contrast to the beneficial metabolic effects, it has been reported that increased plasma leptin levels has the positive correlation with the incidence of various types of cancers." (PMID 29312618, 2017). "In the leptin/adiponectin relationship, this measurement can be considered to be an indicator of sensitivity to insulin in youth who have survived childhood cancer." (PMID 28193268, 2017). "By linking leptin signalling to the established TGFB1 pathway of metastasis / EMT, this study gives a direct mechanism by which leptin can contribute to the poorer outcomes of obese cancer patients." (PMID 28542577, 2017).
cancer (continued). "Leptin also induces VEGFR in cancer cells and promotes angiogenic features in endothelial cells via upregulation/transactivation of VEGFR and downstream expression/activation of Notch." (PMID 28659656, 2017). "In vitro studies using recombinant leptin showed its ability to increase cancer cell proliferation via the activation of ERK1/2 and c-Jun NH2-terminal kinase (JNK) pathways." (PMID 28915700, 2017). "Stimulation of cancer cells with leptin leads to increased aggressiveness and metastatic phenotypes." (PMID 29156726, 2017). "Analogously, adipose tissue also influences cancer progression, particularly for its capacity to act as an endocrine system releasing and controlling biologically active substances (e.g. leptin, adiponectin, TNF-α, etc.)some of which are upregulated in cancer." (PMID 28752333, 2017). "In both non-cancer and cancer granulosa cells, leptin acts as a cyclinD/cdk4, cyclin A/cdk2 and E2F inhibitor." (PMID 28861689, 2017). "In this study, four steps in the cancer progression process were found to be significantly altered by leptin, namely cell proliferation, EMT, invasiveness and cell migration." (PMID 28542577, 2017). "Higher serum levels of leptin have also been reported previously among obese cancer patients as compared to women with normal weight." (PMID 29088874, 2017). "By signaling through its receptor (LEP-R), which is upregulated in certain cancers, leptin can activate the PI3K/Akt/mTOR and Janus kinase/signal transducer and activator of transcription (JAK/STAT) pathways." (PMID 28959684, 2017). "The role of leptin in tumorigenesis was suggested by the high expression of the leptin receptor (ObR) in several cancer cells, such as breast, stomach, colon, ovarian cancers and leukemia." (PMID 28915700, 2017). "Undeniably, adipokines, such as leptin or resistin, promote cancer cell progression via enhancement of cell proliferation and migration, inflammation, promitogenic, and anti-apoptosis pathways, which subsequently can prompt tumor growth and metastatization." (PMID 29188139, 2017). "Leptin and versican are secreted by white adipose, located in whole body, and can in an endocrine, paracrine and autocrine manner, promote cancer proliferation and survival." (PMID 29212223, 2017). "Our studies support consideration of two of these categories for use to reduce the impact of leptin on cancer progression." (PMID 28542577, 2017). "Most research show that leptin and adiponectin have opposite effects on cancer development, being leptin pro-tumorigenic and pro-angiogenic." (PMID 28173833, 2017). "Leptin, a hormone derived from adipose tissue, promotes growth of cancer cells via multiple mechanisms." (PMID 29312618, 2017). "Currently, leptin is also recognized as a polyfunctional cytokine, and it is considered to be involved in the pathogenesis of several cancer types, including breast cancer and pancreatic cancer." (PMID 28160559, 2017). "Given the influence the adipose tissue has on cancer promotion, adipokines such as leptin are investigated to uncover their role on the matter." (PMID 28970834, 2017). "Both leptin and adiponectin are produced within adipose tissue and seem to have opposite effects on the regulation of cancer." (PMID 29212223, 2017). "RSV increases ADIPO:LEP secretion which alters the tumor growth microenvironment such that it supports cell cycle exit of the cancer cells." (PMID 28873415, 2017). "Looking forward, the incorporation of immunohistochemical staining for ketolytic/glycolytic enzymes and biomarkers (i.e. leptin, insulin) and their role in tailoring metabolic cancer management merits further study." (PMID 27525031, 2016). "Accumulated evidence suggests that LPrA are effective inhibitors of leptin signaling and potential novel adjuvants for cancer treatment." (PMID 27472371, 2016). "In humans, particularly obese individuals have higher leptin levels and correspondingly have higher rates of human cancers." (PMID 27525031, 2016).